VCL (vinculin)
Description:
Actin filament (F-actin)-binding protein involved in cell-matrix adhesion and cell-cell adhesion. Regulates cell-surface E-cadherin expression and potentiates mechanosensing by the E-cadherin complex. May also play important roles in cell morphology and locomotion.
Synonyms: MV; VINC; CMD1W; CMH15; HEL114; MVCL
Tractability: Small molecule: a structure with a bound ligand is known; it has a binding pocket of medium quality. Antibody: its Gene Ontology location is reachable by antibodies, with high confidence; UniProt places it where antibodies can reach, with medium confidence. PROTAC: ubiquitination databases record sites on it; its protein half-life has been measured.
Target class: Adhesion
Gene: Protein-coding gene on chromosome 10 (73,995,193 to 74,121,363, forward strand). Ensembl gene ENSG00000035403.
Subcellular location: Cell membrane; Cell junction, adherens junction; Cell junction, focal adhesion; Cytoplasm, cytoskeleton; Cell membrane, sarcolemma; Cell projection, podosome; Cytoplasm, perinuclear region
Subcellular location (Human Protein Atlas): Focal adhesion sites
Pathways (Reactome):
Disease: Paradoxical activation of RAF signaling by kinase inactive BRAF; Signaling by ALK fusions and activated point mutants; Signaling by BRAF and RAF1 fusions; Signaling by RAF1 mutants; Signaling by high-kinase activity BRAF mutants; Signaling by moderate kinase activity BRAF mutants; Signaling downstream of RAS mutants
Cell-Cell communication: Activation of STAT3 by cadherin engagement; Regulation of CDH1 Function
Cellular responses to stimuli: High laminar flow shear stress activates signaling by PIEZO1 and PECAM1:CDH5:KDR in endothelial cells; Turbulent (oscillatory, disturbed) flow shear stress activates signaling by PIEZO1 and integrins in endothelial cells
Hemostasis: Platelet degranulation
Immune System: Neutrophil degranulation
Muscle contraction: Smooth Muscle Contraction
Signal Transduction: MAP2K and MAPK activation
Gene Ontology:
Molecular function: actin binding; alpha-catenin binding; cadherin binding; dystroglycan binding; protein binding; ubiquitin protein ligase binding; beta-catenin binding; structural molecule activity
Biological process: adherens junction assembly; apical junction assembly; epithelial cell-cell adhesion; morphogenesis of an epithelium; platelet aggregation; protein localization to cell surface; regulation of establishment of endothelial barrier; regulation of focal adhesion assembly; regulation of protein localization to adherens junction; cell adhesion; cell-matrix adhesion; lamellipodium assembly; maintenance of blood-brain barrier; negative regulation of cell migration
Cellular component: adherens junction; cell-cell contact zone; cell-cell junction; costamere; extracellular exosome; extracellular vesicle; focal adhesion; protein-containing complex; cell-substrate junction; cytoplasm; cytoskeleton; cytosol; extracellular region; ficolin-1-rich granule lumen; perinuclear region of cytoplasm; plasma membrane; sarcolemma; secretory granule lumen; specific granule lumen; actin cytoskeleton; membrane; myofibril; podosome
Genetic constraint (gnomAD): Loss-of-function variants: 47 observed, 130.08 expected, observed/expected ratio (o/e) 0.36, 90% interval 0.28 to 0.46. The upper end of that interval is the gene's LOEUF score, 0.46, which puts it in group 2 of 6, group 1 being the genes least tolerant of losing a copy. Missense variants: 1,066 observed, 1,519.7 expected, observed/expected ratio (o/e) 0.7, 90% interval 0.67 to 0.74. Synonymous variants: 458 observed, 541.02 expected, observed/expected ratio (o/e) 0.85, 90% interval 0.78 to 0.92.
Gene-disease validity (ClinGen):
ClinGen rates the evidence that VCL causes each of these diseases.
dilated cardiomyopathy 1W (autosomal dominant): Strong.
hypertrophic cardiomyopathy (autosomal dominant): Disputed. A condition in which the myocardium is hypertrophied without an obvious cause.
congenital heart disease (inheritance undetermined): No Known Disease Relationship. A heart disease that is present at birth.
Homologues: Orthologues: chimpanzee VCL (100% identical), macaque VCL (99% identical), pig VCL (99% identical), guinea pig VCL (99% identical), rabbit VCL (99% identical), rat Vcl (98% identical), mouse Vcl (93% identical), dog VCL (92% identical), tropical clawed frog vcl (88% identical), zebrafish vcla (85% identical), zebrafish vclb (74% identical), Drosophila melanogaster Vinc (41% identical), and 1 more. Paralogues in human: CTNNA2 (18% identical), CTNNA1 (18% identical), CTNNA3 (17% identical), CTNNAL1 (12% identical).
Diseases named in the same sentence as VCL in open-access papers:
VCL is named in the same sentence as 176 diseases in open-access papers, as found by Europe PMC text mining. Sharing a sentence is not in itself a finding about the gene and the disease. The quoted sentences say what the papers report.
breast cancer (42 papers, 2011 to 2025). A primary or metastatic malignant neoplasm involving the breast. "Simultaneously, DEHP has been reported to not only mediate drug resistance by activating the vinculin/aryl hydrocarbon receptor (AhR)/ERK signaling pathway but also enhance susceptibility to breast cancer by upregulating the Esr1/HDAC6 pathway in female rats." (PMID 38341560, 2024). "The loss of vinculin is correlated with the development of many cancers, such as squamous carcinoma rhabdomyosarcoma and breast cancer." (PMID 36052248, 2022). "VCL siRNA-loaded CA caused reduced cell viability in both the aggressive forms of breast cancers (MDA-MB-231 and 4T1)." (PMID 31269666, 2019). "Similar findings were reported before as ANXA1 has been shown to be associated with increased metastatic potential in MCF-7 breast cancer cell lines following downregulation of ER and the expression of basal markers (e.g. vinculin)." (PMID 26657294, 2016). "Inhibition of FAK and vinculin causes a significant decrease in normal cell spreading and migration of breast cancer cells." (PMID 21915267, 2011). "Furthermore, we find that ERα is a novel regulator of vinculin expression in breast cancer and that loss of ERα induces amoeboid-like migration of breast cancer cells by regulating vinculin in a 3D matrix." (PMID 28266545, 2017). "A positive association between ERα and vinculin expression is found in human breast cancer tissues." (PMID 28266545, 2017). "In addition, after depletion of vinculin, the activity of MLC increased, thus indicating that loss of vinculin promoted actomyosin contractility in breast cancer cells." (PMID 28266545, 2017). "Regarding the underlying mechanisms, it caused a decrease in the expression of F-actin, vimentin, FAK, and vinculin, leading to changes in the distribution and rearrangement of cytoskeletal proteins in breast cancer cells." (PMID 38563878, 2024). "Through the use of an immunofluorescence test, CuB was found to reduce the intensity of F-actin/vimentin/FAK/vinculin in breast cancer cells." (PMID 38563878, 2024). "This in turn enhanced EZH2 binding to Vinculin and other cytoskeletal regulators, leading to promotion of cell adhesion, migration, invasion and subsequent development of breast cancer metastasis." (PMID 37491334, 2023). "For example, suppression of vinculin in breast cancer cells MCF-7 stimulates the switch of these cells to amoeboid movement in vitro and increases the number of metastasis in vivo experiments in a xenograft mouse model." (PMID 36278174, 2022). "GRK5 affects the migration of non-small cell lung cancer cells through vinculin, moreover, it shows a high expression in breast cancer cells, promotes breast cancer cell metastasis, and is therefore a target for breast cancer treatment." (PMID 36059531, 2022). "A recent study showed that real spaceflight induced the downregulation of vinculin expression and attenuated cell adhesion in human breast cancer cells." (PMID 34068233, 2021). "TWF1 depletion in breast cancer cell line MDA-MB-231 cells drastically reduced vinculin positive focal adhesions, suppressed organization of F-actin, and enhanced the EMT wherein cells acquire spherical morphology." (PMID 34113576, 2021). "VCL directed mutagenesis and overexpression of Tol2-GgVCL or Tol2-VCL/*TBM in MCF-7 human epithelial breast cancer cells showed that VCL/*TBM induced mesenchymal-like changes in cell morphology." (PMID 34123588, 2021). "Regulation of vinculin tension in MDA-MB-231 breast cancer cells is therefore both CAV1- and Gal3-dependent." (PMID 33833286, 2021). "Oestrogen receptor alpha suppressed cell amoeboid-like movement by upregulating VCL, which inhibited breast cancer metastasis." (PMID 34590603, 2021). "Two cell lines derived from MDA-MB-231 breast cancer cells were transfected with the vinculin tension sensor to quantitatively evaluate the force in focal adhesions of the tumor cell." (PMID 30948840, 2019).
breast cancer (continued). "Some of the essential molecules, which are critically involved in breast cancer, are catenins, actinin, talin, vinculin, and paxillin." (PMID 31269666, 2019). "E: Immunofluorescence images for vimentin (green) and liprin-α1 (red) in MDA-MB-231 and Hs578T breast cancer cell lines and for vinculin (green) and liprin-α1 (red) in Hs578T breast cancer cell line after vimentin knockdown." (PMID 30005669, 2018). "Taken together the data suggest that p38-mediated T367 phosphorylation of EZH2 in ER- breast cancer cells promotes a PRC2-independent interaction with cytoplasmic vinculin, leading to phosphorylation of vinculin at Y100 and localization at focal adhesions." (PMID 30022044, 2018). "In this data, VCL was up-regulated by ERα, and the result was consistent with our previous research in which ERα inhibited amoeboid-like migration of breast cancer cells by up-regulating vinculin." (PMID 30301189, 2018). "Using proximity ligation assays (PLA) with confocal imaging, we detected pEZH2(T367)-vinculin interaction (<40 nm apart) in the cytoplasm of breast cancer cells." (PMID 30022044, 2018). "Among the top differential interactors of pEZH2(T367) in the actin-binding set was vinculin, a cytoplasmic membrane and cytoskeletal protein found at focal adhesions with roles in breast cancer migration and invasion." (PMID 30022044, 2018). "Vinculin is overexpressed in human malignancies, including breast cancer, where it regulates cell adhesion and migration." (PMID 30022044, 2018). "Several studies showed that depletion of vinculin renders cells less adherent and more motile, implying a worse prognosis in several types of tumors, including breast cancer." (PMID 28376104, 2017). "The results showed that vinculin abundance was also significantly higher in human primary breast cancer tissues than in lymphatic metastases." (PMID 28266545, 2017). "Our data show that ERα is a novel regulator of vinculin expression in breast cancer and that vinculin is involved in ERα-mediated inhibition of breast cancer cell metastasis." (PMID 28266545, 2017). "Here the authors show that ERα inhibits breast cancer metastasis and suggest that ERα suppresses the amoeboid-like migration of breast cancer cells by upregulating vinculin." (PMID 28266545, 2017). "Together, these results indicated that ERα is a promoter of vinculin expression in breast cancer cells." (PMID 28266545, 2017). "To investigate the role of vinculin, downstream of ERα, in breast cancer metastasis, we performed tail vein injections of control or Cas9-vinculin MCF-7-luc2 cells in athymic mice and examined the expression levels of vinculin by western blotting." (PMID 28266545, 2017). "The results show that ERα inhibits breast cancer metastasis and suggest that ERα suppresses cell amoeboid-like movement by upregulating vinculin." (PMID 28266545, 2017). "In summary, our results demonstrate that ERα suppresses breast cancer metastasis by regulating vinculin." (PMID 28266545, 2017). "Decreased cell–cell adhesion upon vinculin KO was recently observed in the mouse 4T1 breast cancer line and murine skin cells and is in line with the aberrant AJs between cardiac myocytes reported in heart-specific KO of vinculin in mice." (PMID 39547716, 2025). "Similarly, the increased migration persistence we observed in vinculin KO MCF10A cells is in contrast to the decreased persistence observed upon vinculin depletion in MEF KO cells or siRNA-treated mammary carcinoma MDA-MB-231 cells, using different assays." (PMID 39547716, 2025).
breast cancer (continued). "In this work, we compared two breast cancer cell lines with different profiles regarding their aggressiveness, to investigate the treatment mechanisms in Elastic Young’s modulus, spreading rate, adhesion forces, and focal adhesion protein vinculin levels." (PMID 36052248, 2022). "This study aimed to understand the regulation of cell adhesion dynamics and the role of cell adhesion protein vinculin of breast cancer cells prior to and post-treatment with anti-tumor agents and their correlation to cell motility by identifying the cell stiffness and the potential for cell spread." (PMID 36052248, 2022). "Reduced FAK, paxillin, and vinculin levels supported the findings of reduced filopodia and lamellipodia in 4T1 breast cancer cells, which might have resulted in reduced cancer cell migration as visible from large wound size in wound-healing assay." (PMID 34535685, 2021). "However, few studies have described the involvement of vinculin in the regulation of breast cancer amoeboid movement." (PMID 28266545, 2017). "Notably, ERα suppresses the amoeboid-like movement of breast cancer cells by upregulating vinculin in 3D matrix, which in turn promotes cell–cell and cell–matrix adhesion and inhibits the formation of amoeboid-like protrusions." (PMID 28266545, 2017). "To determine whether these characteristics of invadopodia-associated adhesion rings are general or A375-specific, we repeated the experiments, using vinculin labeling of MDA-231 metastatic breast cancer cells." (PMID 25820462, 2015). "To investigate in a clinical setting whether ERα suppresses breast cancer metastasis by facilitating vinculin expression, we measured the expression of vinculin in the same 124 human primary breast cancer tissues and human breast cancer lymph node metastases that were used in the ERα analysis." (PMID 28266545, 2017). "Furthermore, we find that ERα is a novel regulator of vinculin expression in breast cancer." (PMID 28266545, 2017). "We believe that the observed changes in the morphology and impeded motility of the breast cancer cells after exposure to PCAIs are due to the disrupted F-actin organization, depleted levels of RHO GTPases, and vinculin punctate disruption." (PMID 38540084, 2024). "In breast cancer cells transfected with plasmids overexpressing active or inactive ASAP3, cellular vinculin or paxillin in focal adhesion and the distribution of invadopodia were not affected." (PMID 36382054, 2022). "For this purpose, vinculin or talin green fluorescent protein (GFP) fusion proteins, both key constituents of focal adhesions, were expressed in breast cancer cells." (PMID 32511274, 2020). "In this study PF maneuvers induced a downregulation of VCL mRNA and the corresponding protein in MCF-7 breast cancer cells." (PMID 31261642, 2019). "In the current study, we successfully targeted dysregulated CTNNA1, CTNNB1, TLN1, VCL, PXN, and ACTN1 genes by delivering respective siRNAs with the help of nano-sized CA particles in breast cancer cells as well as in a murine breast cancer model." (PMID 31269666, 2019). "Dimercaptosuccinic acid surface coating of SPION enhanced their cellular uptake efficiency without inducing either cytotoxicity, alteration of the major cytoskeletal components, vinculin protein dynamics, cell cycle or ROS formation in MCF-7 breast cancer cell line." (PMID 25880445, 2015). "During breast cancer metastases, EZH2 was shown to be phosphorylated at T367 via p38 MAP kinase which induces cytosolic localization of EZH2 and further promotes EZH2 binding to many cytoskeletal regulators including vinculin which play critical role in cell migration and invasion." (PMID 40289112, 2025). "Furthermore, phosphorylation of EZH2 can mediate its subcellular localization and function, and cytoplasmic pEZH2-T367 enhances breast cancer invasion; in breast cancer cells, p38 phosphorylates EZH2 at T367 to induce EZH2 cytoplasmic localization and binding to vinculin, thereby promoting invasion." (PMID 39409910, 2024).
breast cancer (continued). "Interestingly when vinculin-silenced MSCs were grown on the adhesive surface they gained tumor-suppressing capability as evidenced by reductions of MTT-based cell viability and scratch-based migration of 4T1.2 mammary tumor cells." (PMID 33859739, 2021). "In addition, the mRNA and protein levels of vinculin were higher in ERα-positive breast cancer cell lines than in ERα-negative cell lines." (PMID 28266545, 2017). "We further studied an orthotopic mouse model of breast cancer, using MDA-MB-231 cells stably expressing ERα with or without vinculin knockdown." (PMID 28266545, 2017).
dilated cardiomyopathy (19 papers, 2010 to 2025). Cardiomyopathy which is characterized by dilation and contractile dysfunction of the left and right ventricles. "VCL was known as a susceptible gene for dilated cardiomyopathy (DCM) and hypertrophic cardiomyopathy (HCM)." (PMID 39940965, 2025). "We explored if vinculin (VCL) variants are associated with myocardial recovery in dilated cardiomyopathy (DCM)." (PMID 37548861, 2023). "In mice, heterozygous inactivation or the knockout of vinculin results in dilated cardiomyopathy, and metavinculin deficiency leads to disorganized intercalated discs in human patients." (PMID 33440717, 2021). "Accordingly, in the mouse vinculin loss leads to defects in adhesion complexes that compromise embryonic cardiac development and vinculin+/− mice develop dilated cardiomyopathy." (PMID 20502710, 2010). "As vinculin loss of function is associated with dilated cardiomyopathy, complete inhibition of vinculin function may be maladaptive." (PMID 40869375, 2025). "However, it has been reported that cardiac-specific loss-of-function mutations in vinculin result in dilated cardiomyopathies and sudden cardiac death." (PMID 40869375, 2025). "In addition, a VCL S721C mutation was recently identified in an individual with dilated cardiomyopathy (ClinVar VCV003706424.1)." (PMID 41231303, 2025). "In this study, bioinformatics analyses and multiomics techniques were employed to elucidate the molecular mechanisms underlying dilated cardiomyopathy (DCM) and to identify five potential biomarkers: VCL, ABCB1, JAK2, KDR, and NGF." (PMID 40217309, 2025). "It has been reported that specific removal of VCL gene impairs cellular junctions of cardiomyocytes, resulting in sudden death or dilated cardiomyopathy." (PMID 38287421, 2024). "The variants in VCL, SLC22A5, and FHOD3 have been shown earlier to be associated with HCM or dilated cardiomyopathies (DCM)." (PMID 37342443, 2023). "Cardiac-specific vinculin knockout mice developed left ventricular dysfunction that evolved into dilated cardiomyopathy." (PMID 32661904, 2020). "Vinculin (VCL) interacts with connexins, and cardiac myocyte specific VCL knockout caused Cx43 dislocation, dilated cardiomyopathy, and sudden death." (PMID 24578694, 2014). "Moreover, heterozygous vinculin deletion (+/-) results in dilated cardiomyopathies." (PMID 33440717, 2021). "In the muscle LIM protein (MLP, also called Csrp3)-knockout mouse, a model for dilated cardiomyopathy, the levels of α-catenin, vinculin and F-actin were increased at the intercalated disc, which could well be an adaptive response in supporting the increased mechanical load of the failing heart." (PMID 32661904, 2020).